MTUS2 (microtubule associated scaffold protein 2)
Description:
Binds microtubules. Together with MAPRE1 may target the microtubule depolymerase KIF2C to the plus-end of microtubules. May regulate the dynamics of microtubules at their growing distal tip.
Synonyms: CAZIP; KIAA0774; TIP150; ICIS
Tractability: PROTAC: ubiquitination databases record sites on it; its protein half-life has been measured.
Gene: Protein-coding gene on chromosome 13 (28,820,021 to 29,505,947, forward strand). Ensembl gene ENSG00000132938.
Subcellular location: Cytoplasm, cytoskeleton
Subcellular location (Human Protein Atlas): Cytokinetic bridge; Microtubules
Gene Ontology:
Molecular function: microtubule binding; protein binding; protein homodimerization activity
Cellular component: centrosome; cytoplasmic microtubule; intercellular bridge; microtubule cytoskeleton; nucleus; cytoplasm; cytoskeleton
Genetic constraint (gnomAD): Loss-of-function variants: 37 observed, 97.01 expected, observed/expected ratio (o/e) 0.38, 90% interval 0.29 to 0.5. The upper end of that interval is the gene's LOEUF score, 0.5, which puts it in group 2 of 6, group 1 being the genes least tolerant of losing a copy. Missense variants: 1,671 observed, 1,708 expected, observed/expected ratio (o/e) 0.98, 90% interval 0.94 to 1.02. Synonymous variants: 684 observed, 676.43 expected, observed/expected ratio (o/e) 1.01, 90% interval 0.95 to 1.08.
Homologues: Orthologues: chimpanzee MTUS2 (99% identical), macaque MTUS2 (93% identical), dog MTUS2 (78% identical), pig MTUS2 (71% identical), mouse Mtus2 (70% identical), zebrafish mtus2a (32% identical), guinea pig Mtus2 (23% identical), rat Mtus2 (23% identical), tropical clawed frog mtus2 (15% identical). Paralogues in human: MTUS1 (18% identical), CCDC69 (7% identical).
Diseases named in the same sentence as MTUS2 in open-access papers:
MTUS2 is named in the same sentence as 12 diseases in open-access papers, as found by Europe PMC text mining. Sharing a sentence is not in itself a finding about the gene and the disease. The quoted sentences say what the papers report.
Alzheimer disease (3 papers, 2021 to 2025). A progressive, neurodegenerative disease characterized by loss of function and death of nerve cells in several areas of the brain leading to loss of cognitive function such as memory and language. "Conversely, MTUS2, which encodes a microtubule-associated scaffold protein playing a crucial role in late-onset Alzheimer’s disease (LOAD), exhibited decreased expression across seven distinct cell types." (PMID 40520536, 2025). "Based on previous studies, MTUS2 plays a critical role in cytoskeletal regulation and microtubule assembly and dynamics and is involved in the development of various types of cancers and Alzheimer's disease (AD)." (PMID 41035938, 2025). "Therefore, we speculate that MTUS2, GTPBP6, TIAM-1 and SHROOM2 are likely associated with Alzheimer’s disease." (PMID 33525573, 2021).
Brain atrophy (1 paper, 2020). Partial or complete wasting (loss) of brain tissue that was once present. "Besides the association with TMEM106B in Subtype B, protective variants near MTUS2 were identified which are in close vicinity to HMGB1, a locus that has been previously implicated in brain atrophy." (PMID 32492070, 2020).
breast carcinoma (1 paper, 2025). "The other IL-1β-induced proteins in 6D cells, MTUS2 and TSNAXIP1, have also been associated with the progression of breast cancer and cytoplasmic remodeling." (PMID 40429863, 2025).
Budd–Chiari syndrome (1 paper, 2023). "The lncRNA MTUS2‐5 in EVs plays an important role in angiogenesis in the Budd–Chiari syndrome." (PMID 37596794, 2023).
cardiomyopathies (1 paper, 2024). "Four variants, c.302G>C/p.Gly101Ala (CAPN1), c.637C>T/p.Arg213Trp (MTUS2), c.457C>T/p.Arg153Cys (CRTAC1), c.1309G>T/p.Gly437Cys (UNC45A), were associated with cardiomyopathies." (PMID 38848015, 2024).
gastric cancer (1 paper, 2025). A primary or metastatic malignant neoplasm involving the stomach. "A proteomic analysis of human gastric cancer cells treated with erinacine A revealed notable shifts in protein expression, marked by the upregulation of tumor suppressors 14-3-3σ (1433S) and MTUS2, and a reduction in nucleophosmin (NPM)." (PMID 40959699, 2025).
myocarditis (1 paper, 2024). Myocarditis is a condition that is characterized by inflammation of the heart muscle (myocardium). "The nonsense variant c.1294C>T/p.Arg432Ter in HPSE as well as the missense variant in MTUS2 are associated with myocarditis." (PMID 38848015, 2024).
tumor (3 papers, 2024 to 2025). "High genomic alterations in zesto lesions were inversely correlated with putative tumor suppressor genes (MTUS2, DLGAP3, RTN1, CRLF1, SLC12A5, and PDIA2) and positively correlated with APOBEC mutagenesis (APOBEC3C, APOBEC3G, APOBEC3B, and APOBEC3F) and hypoxia-related gene signatures." (PMID 40319462, 2025). "As for others, CTC, GIGYF1, MTUS2, POM121, PTP14, SPOPL, and ZNF 208 were detected only in tumor tissue, and none were determined to be pathogenic by both algorithms concordantly." (PMID 38254245, 2024).
MTUS2 also shares sentences with these, for which no sentence is quoted: cancer (4 papers); brain tumors (1); schizophrenia (1); thrombosis (1).